CGAS (cyclic GMP-AMP synthase)
Diseases named in the same sentence as CGAS in open-access papers (continued):
Sharing a sentence is not in itself a finding about the gene and the disease.
Aicardi-Goutières syndrome (58 papers, 2015 to 2025). "Aicardi-Goutières syndrome is a monogenic disease caused by mutations in the deoxyribonuclease TREX1 leading to chronic activation of the cGAS-STING pathway." (PMID 39999142, 2025). "Loss of function mutations of TREX1, which were originally described in AGS (Aicardi Goutieres syndrome), result in accumulation of cytosolic DNA inducing a cGAS-dependent type I IFN secretion." (PMID 34381458, 2021). "Biallelic mutations in RNase H2 are linked to a neuroinflammatory disease, Aicardi-Goutières syndrome, presumably through the accumulation of cytosolic DNA fragments and the activation of the DNA sensing cGAS/STING pathway." (PMID 34359660, 2021). "An early-onset autoimmune disorder, Aicardi–Goutières syndrome, has been linked to chronic activation of the cGAS-STING pathway invoking superfluous innate immune responses." (PMID 32576686, 2020). "Similarly, the cGAS-STING pathway is activated by the mutations of RNase H2 found in Aicardi-Goutieres Syndrome patients." (PMID 34819357, 2022). "Small-molecule drugs like aspirin have exhibited notable effects on Aicardi–Goutières syndrome (AGS) by inhibiting cGAS activity and reducing interferon signaling." (PMID 40149865, 2025). "The deleterious effect of rNMPs incorporated into nuclear DNA is illustrated by cGAS–STING-driven inflammatory pathologies caused by mutations of RNase H2 subunits, leading to Aicardi–Goutières syndrome and systemic lupus erythematosus." (PMID 40993386, 2025). "Multiple loss-of-function mutations in the DNA nuclease TREX1 that negatively regulate the DNA stimuli of cGAS-STING results in Aicardi-Goutières syndrome and familial chilblain lupus." (PMID 39999142, 2025). "SAMHD1 inhibits cGAS-STING and NF-κB, and LOF mutations cause Aicardi-Goutières Syndrome (AGS), an autosomal recessive monogenic type I interferonopathy." (PMID 40894167, 2025). "It has also been reported that single-stranded DNA fragments are released from stalled forks and accumulate in the cytoplasm, where they activate the cGAS-STING pathway, causing a severe congenital inflammatory disease known as Aicardi–Goutières syndrome." (PMID 35794098, 2022). "It was found that aspirin acetylates cGAS at three lysine residues and blocks cGAS activity, which has an anti-inflammatory function in Trex1−/− rats and fibroblasts from Aicardi–Goutieres syndrome (AGS) patients." (PMID 36195926, 2022). "We find that a chemically improved member, RU.521, is active and selective in cellular assays of cyclic GMP-AMP synthase-mediated signaling and reduces constitutive expression of interferon in macrophages from a mouse model of Aicardi-Goutières syndrome." (PMID 28963528, 2017). "Similarly, Aicardi–Goutières syndrome (AGS) and COPA syndrome are linked to aberrant cGAS-STING activation, leading to systemic autoinflammatory symptoms." (PMID 40507791, 2025). "Conversely, FA supplementation may benefit the treatment of cGAS‐mediated autoimmune or autoinflammatory diseases such as Aicardi–Goutières syndrome." (PMID 36950761, 2023). "This includes inflammatory syndromes such as STING-associated vasculopathy with onset in infancy (SAVI), Aicardi–Goutières syndrome (AGS), and familial chilblain lupus, but also cGAS related genetic disorders such as TREX1 associated lupus-like autoimmune disorder or Bloom syndrome." (PMID 33708225, 2021). "Mutations in several human genes result in the accumulation and mislocalisation of DNA molecules leading cGAS activation, and this is best exemplified in the form of the Aicardi-Goutières syndrome (AGS), a rare devastating disease characterized by systemic inflammation." (PMID 33117352, 2020). "In addition to immune cells, cGAS is reported to be expressed in astrocytes in vitro and may have a central role in the rare genetic disease Aicardi-Goutières syndrome(AGS), which is characterized by abnormal IFN-I overproduction." (PMID 38467840, 2024).
Aicardi-Goutières syndrome (continued). "Misprocessing of canonical histone transcripts in a subset of Aicardi–Goutières syndrome (AGS) patients with biallelic mutations in LSM11 and RNU7-1 specifically disturbs linker histone stoichiometries and leads to type I IFN signatures by cGAS redistribution and activation within the nucleus." (PMID 35084490, 2022). "This is illustrated in mouse models of Ataxia-telangiectasia and Aicardi-Goutières Syndrome in which genetic depletion of either Interferon Receptor IFNAR, cGAS or STING relieves pathological symptoms." (PMID 35198459, 2022). "Further, autoreactivity of cGAS contributes to Aicardi–Goutières syndrome (AGS), and small molecule inhibition of cGAS activity alleviates constitutive interferon expression in an AGS mouse model." (PMID 33255247, 2020). "In addition, micronuclei levels are increased in cells derived from Aicardi-Goutières syndrome (AGS) patients, a disease characterized by an excess of interferon production and inflammation due to an overactivation of the cGAS/STING pathway." (PMID 36114513, 2022).
lung carcinoma (56 papers, 2017 to 2026). "Some studies have shown that exercise activation of the cGAS-STING signaling pathway can reduce the risk of lung cancer." (PMID 37762143, 2023). "Lung cancer cells develop multiple intrinsic mechanisms to inhibit the cGAS-STING pathway, avoiding surveillance and attack by the immune system by inhibiting this pathway." (PMID 41226461, 2025). "This combination also increased DNA damage and apoptosis in KRAS-mutant lung cancer cell lines, triggering the cGAS-STING pathway." (PMID 41368644, 2025). "In the context of lung cancer, COVID-19, and other virus-induced lung injuries, activation of the cGAS-STING pathway exerts a protective effect." (PMID 41226461, 2025). "It has been reported that activation of the cGAS-STING pathway exhibits significant anti-tumor effects in lung cancer." (PMID 40166469, 2025). "Preclinical studies have shown that cGAS-STING pathway activation can significantly enhance lung cancer patients' response to immunotherapy." (PMID 39439455, 2024). "The possible mechanisms of the Cx43‐mediated cGAS–STING interaction between lung cancer cells and TAMs remain to be further investigated." (PMID 39592436, 2024). "In summary, significant progress has been made in understanding the cGAS-STING pathway in lung cancer, offering critical theoretical support for the development of new therapeutic strategies." (PMID 39439455, 2024). "Understanding the regulation and dysregulation of the cGAS-STING pathway in lung cancer provides invaluable insights into tumor progression and immune evasion mechanisms." (PMID 39834588, 2024). "In lung cancer, activation of the cGAS-STING pathway significantly influences the tumor microenvironment." (PMID 39439455, 2024). "Another previous study reported that knockdown of cGAS inhibited tumor growth through stabilization of the replication forks in lung cancer cells." (PMID 38898119, 2024). "ARID1B knockdown in lung cancer cell lines enhances DNA damage, impairs DNA repair, alters chromatin accessibility, and activates the cGAS-STING pathway." (PMID 38577613, 2024). "In summary, significant strides have been made in unraveling the intricacies of the cGAS-STING pathway in lung cancer, providing a critical theoretical foundation for the development of novel therapeutic strategies." (PMID 39439455, 2024). "The objective of this review is to present a comprehensive overview of the ongoing research on the cGAS-STING signaling pathway within the realm of lung cancer." (PMID 39834588, 2024). "NLRC3, a negative regulator, exhibits considerable potential in the realm of lung cancer immunotherapy by virtue of its profound impact on the immune response intensity, primarily through its regulatory effects on the cGAS-STING pathway." (PMID 39439455, 2024). "Further research is needed to explore the potential and challenges of targeting the cGAS-STING pathway for lung cancer therapy." (PMID 39439455, 2024). "Future research endeavors should prioritize elucidating the intricate mechanisms by which NLRC3 regulates the cGAS-STING pathway in lung cancer and leverage this knowledge to optimize therapeutic strategies." (PMID 39439455, 2024). "Preclinical studies have demonstrated that activating the cGAS-STING pathway can significantly enhance the response of lung cancer patients to immunotherapy." (PMID 39439455, 2024). "In lung cancer, for example, activation of the cGAS-STING pathway exerts a profound influence on the tumor microenvironment." (PMID 39439455, 2024). "Baicalein has been shown to curb mtDNA release and interact with cGAS, thereby inhibiting its activation and mitigating cGAS-mediated inflammation in the context of lung cancer development." (PMID 39834588, 2024).
lung carcinoma (continued). "The purpose of this review is to discuss the immune activation mechanism of cGAS-STING in lung cancer radiotherapy and the mechanism of lung injury and to discuss new therapeutic methods." (PMID 37667279, 2023). "Numerous studies have demonstrated that aberrant activation of the cGAS-STING pathway promotes lung cancer cell proliferation, survival, and invasion, thus contributing to tumour growth and metastasis." (PMID 37667220, 2023). "Studies using mouse and human colon cancer samples, as well as lung cancer model mice and the TCGA lung cancer dataset, found that tumor cells suppress the high-level expression of cGAS and STING through epigenetic regulation or the production of DNase." (PMID 37046775, 2023). "First, we analysed CNV and mutations of STING, cGAS and other STING pathway genes in human lung cancers and 29 other cancer types across ~7800 tumour samples from The Cancer Genome Atlas (TCGA)." (PMID 35794238, 2022). "In lung cancer, there are multiple lines of evidence suggesting that cGAS-STING signaling functions as a tumor suppressor." (PMID 35978045, 2022). "Suppression of the cGAS-STING pathway by nuclear paraspeckle assembly transcript 1 (NEAT1) results in the promotion of lung cancer growth, in syngeneic models, via inhibition of cytotoxic T cell infiltration." (PMID 35978045, 2022). "To assess the status of innate immune activity and its relation to the cGAS/STING pathway key genes in lung cancer types, we then performed a Gene Set Variation Analysis (GSVA) for GO process “Response to Interferon Beta” gene set." (PMID 35794238, 2022). "For example, DNMT1 interacted with NEAT1 to regulate cytotoxic T-cell infiltration in lung cancer via inhibition of the cGAS/STING pathway." (PMID 36226184, 2022). "Our findings demonstrated that NEAT1 interacted with DNMT1 to regulate cytotoxic T cell infiltration in lung cancer via inhibition of cGAS/STING pathway." (PMID 32296457, 2020). "Another study has indicated that the cGAS-STING signaling pathway inhibition due to upregulated nuclear paraspeckle assembly transcript 1 (NEAT1) in the lung cancer cells and tissues." (PMID 33643304, 2020). "Additionally, low cGAS and STING expression was associated with shorter survival in both breast and lung cancer patients." (PMID 40830678, 2026). "Similarly, another study reported that lncRNA NEAT1 interacts with DNMT1 to regulate cytotoxic T cell infiltration by inhibiting cGAS/STING pathway in lung cancer." (PMID 40308809, 2025). "Our findings suggest that MEKi activates the cGAS-STING-TANK-binding kinase 1-nuclear factor kappa B-CXCL10 axis post-radiotherapy in KRAS-mutant lung cancer, increasing T-cell infiltration and function, activating anti-tumor immunity, and inhibiting tumor growth." (PMID 41368644, 2025). "Besides, radiotherapy combined with PD-L1 deletion and autophagy inhibition strategies significantly enhanced the antitumor effects in lung cancer through cGAS-STING-mediated T-cell activation mechanisms." (PMID 40166469, 2025). "Within the intricate immune microenvironment of lung cancer, characterized by a delicate balance of pro-inflammatory and immunosuppressive signals, the cGAS-STING pathway emerges as a central orchestrator governing the dynamic interplay between innate and adaptive immunity." (PMID 39834588, 2024). "However, lung cancer also evades immune surveillance by inhibiting the cGAS-STING signaling pathway through various mechanisms." (PMID 39834588, 2024). "To identify the contribution of cGAS-STING signalling to the TET2-medicated inhibition of lung cancer cell proliferation, migration and invasion, we then treated the vector control and TET2-overexpressing A549 and H1975 cell lines with the cGAS-STING signalling inhibitor RU.521 (10 μM)." (PMID 37667220, 2023).
lung carcinoma (continued). "Activation of the cGAS-STING pathway in lung cancer radiotherapy has shown great antitumor potential by promoting the secretion of type I IFNs, significantly increasing the infiltration of CD + 8 T cells and effectively stimulating anti-tumor immune responses in the body." (PMID 37667279, 2023). "To further confirm the critical role of cGAS-STING signalling in TET2-mediated inhibition of lung cancer cell proliferation and metastasis in vivo, we generated a subcutaneous xenograft model in BALB/c NOD mice (n = 5 group) using vector control and TET2 overexpression cells." (PMID 37667220, 2023). "We aimed to assess whether the ATR inhibitors VE822 and AZD6738, by abrogating the G2 checkpoint, increase cGAS-mediated type I IFN response after irradiation in human lung cancer and osteosarcoma cell lines." (PMID 36387237, 2022). "While one study suggests that cGAS-mediated inhibition of HR repair promotes genomic instability and tumorigenesis in a mouse model of lung cancer, another study reported that inhibition of HR repair by cGAS in mouse bone marrow-differentiating monocytes promotes irradiation-induced cell death." (PMID 35602594, 2022). "For example, agonists that activate the cyclic guanosine monophosphate-adenosine monophosphate synthase-stimulation of interferon genes (cGAS-STING) pathway show promise in eliciting a potent anti-cancer immune response in the tumor microenvironment of different cancers including lung cancer." (PMID 35655772, 2022). "Therefore, the cGAS-STING pathway is a key target in the immune escape mechanism of lung cancer." (PMID 41226461, 2025). "Then evidence regarding the modulation of emerging targets was introduced, namely ferroptosis and the cyclic GMP-AMP synthase-stimulator of interferon genes (cGAS-STING) pathway, which are both promising targets in lung cancer models." (PMID 42094009, 2026). "So, NEAT1, by interacting with DNMT1, inhibits the cGAS/STING pathway, thereby regulating cytotoxic T cell infiltration in lung cancer." (PMID 40387409, 2025). "For example, in lung cancer cells, the inhibition of Cx43 induces macrophage polarization toward the pro-tumor M2 phenotype (TAM) and negatively regulates the cGAS-STING pathway in macrophages, leading to resistance to immune checkpoint inhibitors." (PMID 40416989, 2025). "For example, the combination of cGAS-STING pathway agonists and ICIs has demonstrated significant potential in the treatment of lung cancer." (PMID 41226461, 2025). "Existing research underscores NLRC3's capacity to mitigate excessive immune responses via the negative regulation of the cGAS-STING pathway, thus underscoring its significant regulatory role in lung cancer immunotherapy." (PMID 39439455, 2024). "The inhibition of Cx43 in lung cancer cells can induce macrophage polarisation into TAMs and lead to ICI resistance by negatively regulating the cGAS–STING pathway in macrophages." (PMID 39592436, 2024). "NLRC3, acting as a negative regulator of the cGAS-STING pathway, holds significant promise as a therapeutic target for lung cancer immunotherapy." (PMID 39439455, 2024). "Numerous studies emphasize the critical role of the cGAS/STING pathway in DNA damage sensing, demonstrated in lung cancer, pancreatic cancer, and CRC." (PMID 38609982, 2024). "It is noteworthy that PARP1 trapping can promote IFN signaling through cGAS-STING components, an outcome similar to that reported for RBN2397 inhibition of PARP7 in lung cancer models." (PMID 37077937, 2023). "In many models (immortalized human HCA2-TERT fibroblasts, A549 lung-cancer cells, and LLC tumors in C57BL/6 mice) it is evident that cGAS knockout inhibits tumor growth." (PMID 38139802, 2023).